CYCS (cytochrome c, somatic)
Description:
Electron carrier protein. The oxidized form of the cytochrome c heme group can accept an electron from the heme group of the cytochrome c1 subunit of cytochrome reductase. Cytochrome c then transfers this electron to the cytochrome oxidase complex, the final protein carrier in the mitochondrial electron-transport chain. Plays a role in apoptosis. Suppression of the anti-apoptotic members or activation of the pro-apoptotic members of the Bcl-2 family leads to altered mitochondrial membrane permeability resulting in release of cytochrome c into the cytosol. Binding of cytochrome c to Apaf-1 triggers the activation of caspase-9, which then accelerates apoptosis by activating other caspases.
Synonyms: CYC; HCS; THC4
Tractability: Small molecule: a structure with a bound ligand is known. PROTAC: ubiquitination databases record sites on it; its protein half-life has been measured; a small molecule that binds it is known.
Gene: Protein-coding gene on chromosome 7 (25,118,656 to 25,125,266, reverse strand). Ensembl gene ENSG00000172115.
Subcellular location: Mitochondrion intermembrane space
Subcellular location (Human Protein Atlas): Mitochondria
Pathways (Reactome):
Programmed Cell Death: Activation of caspases through apoptosome-mediated cleavage; Formation of apoptosome; Pyroptosis; Regulation of the apoptosome activity; Release of apoptotic factors from the mitochondria; SMAC (DIABLO) binds to IAPs; SMAC(DIABLO)-mediated dissociation of IAP:caspase complexes
Cellular responses to stimuli: Cytoprotection by HMOX1; Detoxification of Reactive Oxygen Species
Metabolism: Respiratory electron transport
Organelle biogenesis and maintenance: Transcriptional activation of mitochondrial biogenesis
Gene Ontology:
Molecular function: protein binding; electron transfer activity; heme binding
Biological process: apoptotic signaling pathway; cellular respiration; execution phase of apoptosis; intrinsic apoptotic signaling pathway; mitochondrial electron transport, cytochrome c to oxygen; mitochondrial electron transport, ubiquinol to cytochrome c
Cellular component: apoptosome; cytosol; mitochondrial intermembrane space; mitochondrion; nucleus; mitochondrial inner membrane
Genetic constraint (gnomAD): Loss-of-function variants: 0 observed, 8.94 expected, observed/expected ratio (o/e) 0, 90% interval 0 to 0.34. That is too few expected variants to judge how well the gene tolerates losing a copy. Missense variants: 87 observed, 129.93 expected, observed/expected ratio (o/e) 0.67, 90% interval 0.56 to 0.8. Synonymous variants: 41 observed, 43.79 expected, observed/expected ratio (o/e) 0.94, 90% interval 0.73 to 1.22.
Gene-disease validity (ClinGen):
ClinGen rates the evidence that CYCS causes each of these diseases.
thrombocytopenia 4 (autosomal dominant): Limited.
Homologues: Orthologues: chimpanzee CYCS (100% identical), macaque CYCS (99% identical), mouse Cycs (91% identical), mouse Gm10053 (91% identical), rat Cycs (91% identical), rat Cycs-ps9 (91% identical), rat AC128290.1 (90% identical), dog CYCS (90% identical), Drosophila melanogaster Cyt-c-d (66% identical), Caenorhabditis elegans cyc-2.2 (56% identical), Caenorhabditis elegans cyc-2.1 (55% identical).
Diseases named in the same sentence as CYCS in open-access papers:
CYCS is named in the same sentence as 326 diseases in open-access papers, as found by Europe PMC text mining. Sharing a sentence is not in itself a finding about the gene and the disease. The quoted sentences say what the papers report.
breast carcinoma (126 papers, 2002 to 2025). "On the other hand, elevated CYCS transcript levels were associated with reduced OS and increased metastasis risk in a mixed breast cancer cohort of all subtypes." (PMID 40806359, 2025). "Generally, our study identified three mRNAs (TBX21, TGIF2, and CYCS) that were significantly altered between high‐ and low‐risk patients with breast cancer." (PMID 30632703, 2019). "These divergent results highlight the complex biological role of CYCS and the context, cohort (molecular subtype, grade, stage) and test dependence of its study results in breast cancer." (PMID 40806359, 2025). "Additionally, in a TNBC subset of breast cancers of all subtypes, low CYCS and high VDAC1 (voltage-dependent anion channel-1) protein levels were linked significantly to reduced 5-year DFS." (PMID 40806359, 2025). "Studies have found that CYCS, as hub gene, not only plays an important role in the pathophysiology of ovarian cancer, but also has a vital function in bone metastasis of breast cancer and the prognosis of cervical cancer." (PMID 36173462, 2023). "Furthermore, the steady-state CYCS level in breast cancers is excessively reduced compared to healthy tissue, which may hinder the accurate assessment of its expression in cancer." (PMID 40806359, 2025). "Total findings concluded that PARP cleavage, CYCS releasing, caspase-8, and enhanced expression of FADD authenticates the A. fragrantissima induces apoptosis in breast cancer MCF-7 cells." (PMID 38820323, 2024).
melanoma (64 papers, 2006 to 2026). A malignant, usually aggressive tumor composed of atypical, neoplastic melanocytes. "BCL10 (3.84-fold), TRADD (2.71-fold), CYCS (2.51-fold), DIABLO (2.43-fold), BAD (2.36-fold), BID (2.17-fold), TNFSF8 (2.13-fold), TNFSF10 (2.11-fold), BAX (2.03-fold), and FAS (2.01-fold) were also proapoptotic genes highly upregulated in response to UA treatment in A-375 melanoma cells." (PMID 39473730, 2024).
prostate carcinoma (58 papers, 2007 to 2025). A carcinoma that arises from epithelial cells of the prostate gland. "The two clusters showed significant differences in the expression of PRGs; CHMP2A, CHMP4C, CYCS, CASP6, CASP8, GPX4, and TIRAP have high expression levels in cluster B, suggesting that these genes may associate with poor prognosis in prostate cancer." (PMID 35813821, 2022). "In addition, we used qRT-PCR to compare the expression of hub genes (CHMP4C, GSDMB, NOD2, PLCG1, CYCS, GPX4) between prostate cancer cell lines (LNCap, PC3, DU-145) and the normal prostate epithelial cell line (RWPE-1)." (PMID 36386841, 2022).
lung carcinoma (57 papers, 2006 to 2025). "IHC results also confirmed that GALNT3, CYCS, EIF5A, and ITGB4 were highly expressed in lung cancer tissues than normal lung tissues." (PMID 35651789, 2022). "The results showed that miRNA may be involved in the regulation of several lung cancer driver genes, such as BCL2, CYCS, E2F2, MCL1, or MYC, among others." (PMID 38791013, 2024).
colon carcinoma (56 papers, 2006 to 2025). "Allicin can induce apoptosis in the colon cancer HCT116 cell line via the mitochondrial-dependent pathway, as it results in an increase in CYCS and apoptosis regulator BAX protein level but a reduction in the expression of the anti-apoptotic protein BCL2." (PMID 36497321, 2022). "For example, administration of crude extract of garlic to a human colon cancer cell line induced apoptosis by increasing the levels of BAX, CYCS (previously known as cytochrome c) and CASP3 activity while it decreased the mitochondrial membrane potential." (PMID 19552815, 2009).
hepatocellular carcinoma (49 papers, 2010 to 2026). A malignant tumor that arises from hepatocytes. "USP53 enhanced the stability of cytochrome c (CYCS) in hepatocellular carcinoma (HCC) cells by blocking ubiquitination and subsequent degradation to induce apoptosis." (PMID 38904030, 2024). "To test this possibility, we measured the levels of ATP and the abundance of proteins CYCS, NDUFB6, and UQCRB in Hepa1–6 cells (mouse hepatoma cells)." (PMID 32546794, 2020).
Sepsis (28 papers, 2011 to 2025). Sepsis is defined as life-threatening organ dysfunction caused by a dysregulated host response to infection. "Moreover, transcript levels of the pro-apoptotic genes BAK1, CYCS, BBC3, CASP7, and CASP8 were upregulated in the COVID-19 cohort, whereas those of anti-apoptotic genes, such as BCL2L11 and BCL2L1, were upregulated in the sepsis cohort." (PMID 36443881, 2022).
cervical carcinoma (26 papers, 2007 to 2025). A carcinoma arising from either the exocervical squamous epithelium or the endocervical glandular epithelium. "It has also been reported that after pretreatment of HPV16-positive and HPV18-positive human cervical cancer cell lines with colchicine for 48 h, there was a significant increase in CYCS expression in the cytoplasm." (PMID 37405052, 2023).
colorectal cancer (26 papers, 2004 to 2025). A primary or metastatic malignant neoplasm that affects the colon or rectum. "Specifically, we found that a subgroup of seven genes – BIRC5, CYCS, FZD3, FZD8, MAPK9, SMAD3, and SOS1 – that belong to the KEGG colorectal cancer pathway showed significant association with risk of BCC." (PMID 27367190, 2016).
diabetes (25 papers, 2007 to 2025). "Similarly, the apoptotic regulators CASP3 (caspase-3) and CYCS (cytochrome C), both targeted by our miRNA candidates, are central to neuronal loss in AD and β-cell dysfunction in diabetes, further underscoring the shared mechanisms of programmed cell death in these disorders." (PMID 41385529, 2025).
gastric cancer (25 papers, 2013 to 2025). A primary or metastatic malignant neoplasm involving the stomach. "Available studies have shown that colchicine promotes the release of CYCS to activate apoptosis in acute lymphoblastic leukemia, as well as the release of CYCS to induce apoptosis in gastric cancer cells and inhibit growth of gastric tumors." (PMID 37405052, 2023).
lymphoma (21 papers, 2001 to 2025). A malignant (clonal) proliferation of B- lymphocytes or T- lymphocytes which involves the lymph nodes, bone marrow and/or extranodal sites. "In the CSF + LM (lymphoma) vs. CSF − LM comparison, ITGB1, IL6, ABL1, CYCS, among others, were differentially observed and expressed in cancer cells." (PMID 35053611, 2022).
ovarian carcinoma (21 papers, 2011 to 2025). A malignant neoplasm originating from the surface ovarian epithelium. "Oncoprint profile of CYCS, VEGFA, IL6, UQCRC1, UQCRFS1, COX5B, ACKR3/CXCR7, and FYN indicated that these genes were either amplified or overexpressed in 4–25% of the ovarian cancer patients." (PMID 34439877, 2021). "The identification of CYCS, VEGFA, IL6, UQCRC1, UQCRFS1, COX5B, ACKR3/CXCR7, and FYN as pro-tumorigenic nodes designates them as the novel and potentially druggable targets for effective targeted adjuvant therapy for ovarian cancer." (PMID 34439877, 2021).
glioblastoma (20 papers, 2010 to 2025). The most malignant astrocytic tumor (WHO grade IV). "In the anticancer efficacy study of medicarpin on U251 and U87 glioblastoma cells, it was found that medicarpin increased apoptosis in cancer cells by increasing BAX, CYCS and CASP3 gene levels and also decreased Bcl‐2 levels." (PMID 40318008, 2025). "We found that BAX, CYCS and CASP3 levels amplified and Bcl‐2 levels reduced in U251 glioblastoma cells to which we applied BA at different doses." (PMID 40318008, 2025).
viral infection (15 papers, 2010 to 2023). "Moreover, proteins that interact with CYCS are associated with the response to and occurrence of viral infections and neurodegenerative diseases." (PMID 35754951, 2022). "CYCS regulates the intrinsic apoptotic pathway and is altered during viral infections." (PMID 37264422, 2023). "For example, G2/I2 showed hyper-editing of type 1 interferon (IFN) receptors (IFNAR1 and IFNAR2), type 1 IFN-stimulated genes (ISGs) (e.g., EIF2AK2, DDX58/RIG-1, MAVS, TRIM56, and TRIM69) and genes involved in immune responses to viral infection (EIF2AK2, DDX58/RIG-1, MAVS, CASP8, CYCS, and HMGB1)." (PMID 35406793, 2022).
Alzheimer disease (14 papers, 2007 to 2024). A progressive, neurodegenerative disease characterized by loss of function and death of nerve cells in several areas of the brain leading to loss of cognitive function such as memory and language. "GSEA results verified CYCS was mainly enriched in Alzheimer diseases and mitotic spindle." (PMID 35502302, 2022).
breast tumor (8 papers, 1971 to 2025). "Then, in contrast to normal breast tissue, breast tumor tissue had considerably lower MAOB expression levels and higher levels of CYCS, XBP1, HSPA4, APEX1, and SERP1." (PMID 41367017, 2025). "Genes associated with the cardiotoxicity of doxorubicin (through negative effects on mitochondrial function when converted to doxorubicinol) also have altered expression in breast tumour cells upon selection for doxorubicin resistance, including ACO1, ATPS, CYCS, and ATP2B4." (PMID 22938713, 2012).
Thrombocytopenia (8 papers, 2015 to 2024). A reduction in the number of circulating thrombocytes. "The variant interferes with protein expression, increases mitochondrial activity and reduces basal caspase activity, a reduction that is distinct among thrombocytopenia‐causing CYCS gene variants." (PMID 39191490, 2024). "The CYCS gene is highly evolutionarily conserved, with only a few pathogenic variants that cause thrombocytopenia‐4 (THC4)." (PMID 39191490, 2024). "Thrombocytopenia 4 is a sporadic form of inherited thrombocytopenia caused by variants in the CYCS gene (cytochrome c)." (PMID 39191490, 2024). "Our findings demonstrated that a new missense variant of the CYCS gene was associated with non-syndromic thrombocytopenia identified by WES." (PMID 35126455, 2021). "A loss of function deletion in the CYCS gene has recently been linked to non-syndromic thrombocytopenia in a Japanese family." (PMID 33426505, 2020). "This meant it was not possible to isolate clonal megakaryocytic cell lines with stable overexpression of mutant cytochromes c for investigation of the underlying biology of CYCS-associated thrombocytopenia." (PMID 29287084, 2017). "Thrombocytopenia Cargeeg (THC4; OMIM 612004) is one of two autosomal dominant thrombocytopenias associated with the only known mutations of the human cytochrome c gene (CYCS)." (PMID 26086723, 2015). "However it is unlikely that CYCS-associated thrombocytopenia is related to a requirement for increased levels of respiratory chain complexes in differentiating megakaryocytes." (PMID 29287084, 2017). "The molecular basis of CYCS-associated thrombocytopenia therefore requires further investigation." (PMID 29287084, 2017). "However the underlying molecular basis of CYCS-associated thrombocytopenia and the specific role of cytochrome c in platelet formation are unknown." (PMID 29287084, 2017). "To further investigate the origin of thrombocytopenia, we focused on CYCS's roles in the respiratory chain and apoptosis." (PMID 39191490, 2024). "Thrombocytopenia 4 (THC4; OMIM 612004) is an inherited autosomal disease, which occurs due to mutations in the human cytochrome c gene (CYCS) resulting in enhanced mitochondrial apoptotic activity." (PMID 27461282, 2016). "So far, there are only 4 pedigrees with nonsyndrome thrombocytopenia and 1 pedigree with hemophilia A, associated with variants in CYCS gene." (PMID 35126455, 2021).
Thrombocytopenia (continued). "Other ITs to consider which may also present with thrombocytopenia with normal platelet size include RUNX1-related thrombocytopenia (RUNX1-RT), ETV6-related thrombocytopenia (ETV6-RT) and CYCS-related thrombocytopenia (CYCS-RT)." (PMID 35587581, 2022).
Cognitive impairment (6 papers, 2020 to 2025). Abnormal cognition is characterized by deficits in thinking, reasoning, or remembering. "We can speculate that high CYCS expression is an early neuronal apoptotic marker and early application of CYCS-targeted drugs for patients with dry rhinitis and AR can effectively inhibit nasal peripheral nerve atrophy and prevent the occurrence of cognitive impairment." (PMID 35754951, 2022).
esophageal cancer (5 papers, 2014 to 2023). A primary or metastatic malignant neoplasm involving the esophagus. "qRT-PCR detection demonstrated increased expression of MPC1, COX6C, CYB5R3, CASP7, and CYCS in esophageal cancer patients." (PMID 38196829, 2023). "In patients with stage IV esophageal cancer CYCS (p = 0.014), PON3 (p = 0.14), ACPP (p = 0.047), and RPL22 (p = 0.047) were significantly upregulated compared with patients with early-stage cancer." (PMID 33828156, 2021). "Our results showed that the levels of MPC, COX6C, CYB5R3, CASP7, and CYCS were significantly upregulated in tumor tissues compared with adjacent non-tumor tissues in esophageal cancer patients." (PMID 38196829, 2023). "In addition, we found by qRT-PCR that the levels of MPC1, COX6C, CYB5R3, CASP7, and CYCS in tumor tissues of esophageal cancer patients were significantly higher than adjacent non-tumor tissues, suggesting that these genes may have some value in clinical diagnosis and prognosis." (PMID 38196829, 2023).
psoriasis (5 papers, 2018 to 2025). An autoimmune condition characterized by red, well-delineated plaques with silvery scales that are usually on the extensor surfaces and scalp. "Subsequently, WGCNA showed the hub genes (e.g., S100A12, CYCS, NOD2, STAT1, HSPA4, AIM2, MAPK7), which were significantly associated with clinical phenotype, PANoptosis signature, and identified immune response in psoriasis." (PMID 38125299, 2024).
triple-negative breast carcinoma (4 papers, 2022 to 2024). An invasive breast carcinoma which is negative for expression of estrogen receptor (ER), progesterone receptor (PR), and human epidermal growth factor receptor 2 (HER2). "Meanwhile, CYCS expression levels have been found to be upregulated in triple-negative breast cancer, and its effects have rarely been studied." (PMID 35309514, 2022).
atherosclerosis (3 papers, 2020 to 2023). A disease characterized by the build-up of fatty material and calcium deposition in the arterial wall resulting in partial or complete occlusion of the arterial lumen. "Both MPO and CYCS are key targets with the highest degree values, and there are numerous studies demonstrating the involvement of MPO in the development and progression of atherosclerosis." (PMID 37405052, 2023).